ABCG2 (ATP binding cassette subfamily G member 2 (JR blood group))
Diseases named in the same sentence as ABCG2 in open-access papers (continued):
Sharing a sentence is not in itself a finding about the gene and the disease.
lung carcinoma (continued). "According to these findings it was concluded that cigarette smoking promotes lung cancer cell chemoresistance, through ABCG2 upregulation mediated by AKY activation, and expands the cancer stem-like cell population, further contributing to drug resistance." (PMID 30060526, 2018). "Our ChIP data indicated that YAP1 directly regulated ABCG2 expression at the transcriptional level in H460 lung cancer cells." (PMID 27911857, 2017). "In lung cancer cells, ATP-binding cassette sub-family G member 2 (ABCG2), an ABC transporter member, is responsible for SP formation." (PMID 27911857, 2017). "Disruption of YAP1 expression by siRNA attenuated the expression of ABCG2 transcript and significantly reduced the percentage of SP cells and sphere formation in lung cancer cells." (PMID 27911857, 2017). "Compound stimulated ATPase activity and inhibited ABCG2 arbitrated transport at concentration >10 μM and induced ABCG2 expression in lung cancer cells." (PMID 28097641, 2017). "ABCG2 contributes to chemotherapeutic drug resistance in lung cancer treatment and appears to be a predictor of survival in patients with advanced non-small cell lung cancer." (PMID 27911857, 2017). "Other types of lung cancer cells, such as H460 cells, also exhibited ABCG2 protein stimulation by 83.7% when treated by these compounds." (PMID 28881812, 2017). "Our finding expands what is known about YAP1-promoted drug resistance through regulating a well-known ABC-transporter, ABCG2, in lung cancer." (PMID 27911857, 2017). "Overexpression of YAP1 in lung cancers led to an increase in ABCG2 expression and increased the percentage of SP cells." (PMID 27911857, 2017). "It has been shown, indeed, that Nrf2 silencing attenuates the expression of the ABCG2 transcript and protein and sensitises lung cancer cells to mitoxantrone and topotecan, two representative chemotherapeutic drugs effluxed mainly by the presence of ABCG2." (PMID 26697129, 2016). "To study the role of DR-H23 cells in cisplatin-resistant lung cancer, we used western blotting to measure the expression of two important genes related to drug resistance, ABCG-2 and MDR-1." (PMID 26872057, 2016). "In lung cancer cell lines it was shown that ABCG2 has a typical role in the regulation of cell proliferation." (PMID 27171227, 2016). "Considering such multifactorial contribution of ABCG2 in lung cancer pathogenesis, the novel finding of the current study associating the modulation of ABCG2 expression within the EMT program and the S1P biology is of particular interest." (PMID 26967245, 2016). "Our findings indicate that gefitinib, in lung cancer cells, inhibits ABCG2 activity, as previously reported." (PMID 26536031, 2015). "Breast cancer resistance protein (BRCP/ABCG2) is a major drug transporter in protecting lung cancer SP cells from cytotoxic agents." (PMID 24009622, 2013). "We showed that a low concentration of ethanol, which inhibits many membrane proteins, inhibits ABCG2 in lung cancer SP cells." (PMID 24009622, 2013). "In conclusion, our studies suggest that LMWH reduces lung cancer chemoresistance via inducing ABCG2 protein degradation through the proteasome pathway." (PMID 22844424, 2012). "The ABCG2-transduced human lung cancer PC-9 (PC-9/ABCG2) cells showed gefitinib resistance evidenced by their lower accumulation and higher efflux of gefitinib than their parental cells." (PMID 23691449, 2012). "A subpopulation, named side population (SP) with higher ABCG2 expression level in human cancer cells including lung cancer A549 cells, showed series of CSCs’ characteristics." (PMID 22768056, 2012). "For instance, the side population of lung cancer cell line H460 preferentially expresses ABCG2 and SMO, a critical mediator of the hedgehog signaling." (PMID 22768056, 2012).
lung carcinoma (continued). "Next, to further strengthen the role of BCRP/ABCG2 in influencing gefitinib sensitivity, the correlation between BCRP/ABCG2 expression and gefitinib sensitivity was evaluated in various lung cancer cell lines, which express either wild-type or mutated EGFR." (PMID 21731744, 2011). "The BCRP/ABCG2 expression was only detected in the gefitinib-insensitive lung cancer cells bearing wtEGFR (A549)." (PMID 21731744, 2011). "Markers such as ESA, CXCR4, ALDH and ABCG2 have been used with CD133 for isolating CSC from lung cancers." (PMID 21124918, 2010). "The current study demonstrated the efficacy of FA-mExo siRNA-c-kit in overcoming gefitinib resistance both in vitro and in vivo, primarily by attenuating stemness features, including the reversal of EMT and reduction of ABCG2 expression levels in gefitinib-resistant lung cancer cells." (PMID 39744423, 2025). "Second, QB1561 at low concentrations, could partially reverse resistance of mitoxantrone or topotecan mediated in ABCG2-overexpressing NCI-H460/MX20 lung cancer cells, suggesting it can serve as a new ABCG2 regulator." (PMID 40066335, 2025). "We analyzed the potential involvement of hemin combination to improve the efficacy of ALA-PDT to induce cell death in A549 lung cancer and hypothesized that it regulates the PpIX accumulation by repressing the ABCG2 and ABCB1 expression." (PMID 39584916, 2024). "Moreover, several stem cell factors are reported to be important CSC markers in lung cancer, such as octamer-binding transcription factor 4 (Oct4, encoded by the POU5F1 gene), Nanog homeobox (Nanog, encoded by the NANOG gene) and ABCG2." (PMID 37726816, 2023). "Therefore, the knockdown of SOX4 decreased miR-130a-3p-induced cisplatin resistance in cisplatin-resistant lung cancer cells by reducing ABCG2 expression." (PMID 36778005, 2023). "Treatment of lung cancer cells with tobacco concentrates can lead to significant upregulation of ABCG2 and its transcription factors Sp1 and Nrf2, indicating that smoking may induce lung cancer partly through ABCG2 upregulation." (PMID 35719973, 2022). "Accordingly, CD133+ABCG2+ subpopulation cells could be spared from cisplatin treatment in mice xenografts established from human primary lung cancers." (PMID 35956408, 2022). "Moreover, we showed that NAC treatment also restored the expression of ALDH1A1 and ABCG2 in apatinib-treated lung cancer cells." (PMID 33980809, 2021). "As NCI-H460 is a lung cancer cell line, and S1 is a colon cancer cell line, it might, to some extent, develop other mechanisms of drug resistance apart from overexpressing ABCG2." (PMID 33658942, 2021). "Our previous basic experiments established that FYN combined with chemotherapeutic drugs induces apoptosis in lung cancer cells and moreover, downregulates the side population (SP) of lung cancers cells, which was reflected by the inhibition of ABCG2 protein expression." (PMID 34277435, 2021). "RT-qPCR and IHC staining assays here demonstrated that the expression levels of lung cancer markers and cancer stem cell features of lung cells, including Kras, c-Myc, ABCG2, OCT4, SOX2 and Aldh1a1, were markedly increased in lung tissues of PM2.5-challenged mice." (PMID 32554855, 2020). "Similarly, the lung cancer stem markers ABCG2, CD133, and CD44 were also suppressed by the combination of FO and Se." (PMID 32751169, 2020). "In this study, we aimed to investigate whether M3814 can modulate ABCG2-mediated MDR in lung cancer." (PMID 32477940, 2020). "Similarly, we found that the ABCG2-overexpressing human S1-M1-80 colon cancer cells and the ABCG2-overexpressing human H460-MX20 lung cancer cells are equally sensitive to sitravatinib as their parental S1 and H460 cancer cells, respectively." (PMID 31941029, 2020). "Expression of ABCG2 has been reported in both lung cancer and breast cancer, suggesting that it may influence tumor resistance and the pharmacokinetics of EGFR TKIs." (PMID 31340525, 2019).
lung carcinoma (continued). "Finally, in another recent study the same authors have explored the molecular mechanisms through which cigarette smoking stimulates ABCG2 expression in lung cancer cells." (PMID 30060526, 2018). "Moreover, the YAP1 inhibitor verteporfin and YAP1 siRNA downregulated ABCG2 level through inhibition of YAP1 in lung cancer cells and sensitized them to the chemotherapy drug doxorubicin." (PMID 27911857, 2017). "Consequently, determining the molecular mechanism that controls ABCG2 expression in lung cancer is very important for developing more effective therapy that can downregulate ABCG2 and lead to eradication of cancer stem cells." (PMID 27911857, 2017). "ABCG2 is the major contributor of the SP cell properties of lung cancer cells." (PMID 27911857, 2017). "Together, the results obtained with the murine lung cancer model and analysis of patient cohorts suggested that miR-494-3p and, to a lesser extent, chromosome 14 miRNA cluster correlated with a more invasive, ABCG2-positive phenotype in NSCLC." (PMID 27980227, 2017). "Our study adds a new function for YAP1 that may be relevant to drug resistance and cancer therapy through regulation of ABCG2 and side population cell formation in lung cancer." (PMID 27911857, 2017). "Low levels of ABCG2 were intrinsically expressed in lung cancer cell lines NCI-H460 and A549." (PMID 24980828, 2014). "In addition, an inverse correlation between promoter methylation of ABCG2 and its expression in lung cancer and multiple myeloma has been determined." (PMID 24380367, 2013). "For example, there were no published data for gastric cancer, nervous system neoplasm and lung cancer with association of ABCG2 C421A published up to now; we did not posses enough statistical power to detect the precise association." (PMID 22937733, 2012). "Therefore, the aim of this study was to explore the anticancer activity of ART and to investigate the effects of ART on the expression of EGFR and ABCG2 in A549 human lung cancer cells and a mouse xenograft model." (PMID 22183882, 2011). "Ho and colleagues isolated and characterized SP cells from six human lung cancer cell lines and showed that an elevated expression of ABCG2 as well as other ATP-binding cassette transporters were positively correlated with resistance to multiple chemotherapeutic drugs." (PMID 18612434, 2008). "The reversal effect of CC-671 is mainly due to the inhibition of ABCG2 drug efflux activity, resulting in an increase in intracellular chemotherapeutic drug levels, which can improve the efficacy of chemotherapeutic drugs on ABCG2-overexpressing lung cancer cells." (PMID 35784389, 2022). "However, it is not currently known whether TGF-β1 could directly regulate the expression of ABCG2 in lung cancer." (PMID 35684095, 2022). "Similarly, the ABCG2-overexpressing multidrug-resistant H460-MX20 human lung cancer cells, S1-M1-80 human colon cancer cells, ABCG2-transfected R482-HEK293 cells, and the corresponding drug-sensitive parental H460, S1 and pcDNA-HEK293 cells are also equally sensitive to erdafitinib treatment." (PMID 32466597, 2020). "Interestingly, 10 or 20 μM of cariprazine significantly decreased the expression levels of the ABCG2 protein in the colon and lung cancer cell lines, suggesting that cariprazine inhibits both the function and expression of ABCG2 transporters at nontoxic concentrations." (PMID 30181510, 2018). "In this study, we asked whether YAP1 regulates ABCG2 in lung cancer cells." (PMID 27911857, 2017).
lung carcinoma (continued). "Consequently, we determined whether masitinib could also reverse MX resistance in an ABCG2 overexpressing H460/MX20 lung cancer cell line that specifically confers resistance to MX." (PMID 24626598, 2014). "Thus, more studies are needed to investigate whether over-expression of Oct-4, CD133, and/or ABCG2 play a role in the development of MDR in LC-CD133+ or surrogate markers of therapeutic response in patients with lung cancer." (PMID 18612434, 2008). "This stabilization was shown to increase the binding of AHR to the promoter regions of the stemness genes such as ABCG2, KLF4, and cMYC, promoting tumor growth and enhancing lung cancer stem-like properties." (PMID 40303305, 2025). "Upregulated genes in pathological ECs vs. healthy ECs include ABCG2, also known as breast cancer resistance protein (BCRP) and lipid phosphate phosphatase-related protein type 5 (PLPR5), found in lung cancer and in breast tumors." (PMID 34445568, 2021). "Since ABC transporters are critical for drug resistance, the levels of P-gp, ABCG2, and MRP1 were studied and found to be increased in Taxol-induced T24 lung cancer cells compared with A549 cells or other resistant cell lines." (PMID 33846536, 2021). "Vanillin, a major component in Vanilla planifolia seed, reduces CSC phenotypes in lung cancer cells and downregulates CSC markers CD133, ALDH1A1 and ATP-binding cassette super-family G member 2 (ABCG2)." (PMID 34832867, 2021). "For example, in head and neck carcinoma, lung carcinoma, and choriocarcinoma cell lines, the AHR regulates expression of an ABC transporter, ABCG2, which contributes to chemoresistance by exporting drugs out of the cell against a concentration gradient." (PMID 33396563, 2020). "Thus, the role of ABCB1 and ABCG2 methylation in lung cancer remains unclear to date." (PMID 33066132, 2020). "Messenger RNA levels of ABCB1 (MDR1), ABCG2 (BCRP), ABCC1 (MRP1), and ABCC2 (MRP2) genes in lung cancer cells and their resistant sublines were evaluated by RT-PCR." (PMID 30841620, 2019). "More importantly, a previous study revealed that KLF5 transcriptionally repressed the expression of ATP-binding cassette subfamily G member 2 (ABCG2) and KLF5 knockdown increased the resistance of lung cancer cells to doxorubicin treatment." (PMID 29898734, 2018). "Corresponding to previous studies, we isolated SP cells with high mRNA expression of ABCG2, OCT4, and NANOG genes and high proliferative potential from gefitinib-resistant NCI-H460 lung cancer cells." (PMID 28219421, 2017). "For example, in lung cancer cells, overexpression of SP1 can upregulate the expression of ABCG2, which is one of the ATP binding cassette (ABC) transmembrane proteins that influence the chemotherapeutic resistance of cancer cells." (PMID 26922862, 2016). "In lung cancer-derived CD133-positive cells (LC-CD133 (+)), higher Oct-4 expression coexpressed the multiple drug-resistant marker ABCG2 and showed significant resistance to chemotherapy agents and radiotherapy." (PMID 23984394, 2013). "QB1561 was able to partially reverse the resistance of mitoxantrone and topotecan in lung cancer NCI-H460/MX20 cells which overexpressed ABCG2, without altering the expression levels of ABCG2." (PMID 40066335, 2025). "NF‐κB not only enhances ABCG2 transcription but also promotes its membrane localization, facilitating the development of multidrug resistance (MDR) in various cancers, including acute myeloid leukemia and non‐small cell lung cancer (NSCLC)." (PMID 40654246, 2025). "This means that the evaluation of ABCG2 mRNA in the peripheral blood cells is most likely not suitable for assessing the effectiveness of therapeutic interventions in lung cancer patients." (PMID 39457707, 2024). "The reproducible resistance mechanism observed in MIA PaCa-2 cells was distinct from KRAS-mutant colon and lung cancer models, which evidenced neither ABCG2 upregulation nor resensitization to ERK inhibition by pharmacologic ABCG2 inhibition." (PMID 38822082, 2024).
lung carcinoma (continued). "The study showed that targeting P110α and P110β using CRISPR/Cas9 technology could reduce the expression of ABCB1(P-gp) and ABCG2 (BCRP), and partially enhance colchicine and paclitaxel sensitivity in epidermoid carcinoma and lung cancer cells." (PMID 35715750, 2022). "The expression levels of CD44, SOX2, Nanog, Oct4, and ABCG2 in lung cancer nodules from Tumor + CIH groups were significantly upregulated compared with the lung cancer tissues from Tumor + Nor mice." (PMID 33596919, 2021). "Moreover, lung cancer stem cells express “stemness”-related biomarkers, such as CD44, CD24, CA133, CD13, CD90, ABCG2, SOX2, and EPCAM." (PMID 32849930, 2020). "Consistent with our findings, it has been reported that MRP protein rather than MDR1 or ABCG2 appears to play a more significant role in Drug resistance in lung cancer." (PMID 33097055, 2020). "In this study, we found that Apatinib could inhibit the expressions of stemness biomarkers ABCG2, CD24, ICAM-1, OCT4, and SOX2 in lung cancer." (PMID 32849930, 2020). "According to the real-time PCR detection results, for the surface marker-related genes of lung cancer stem cells, the expressions of CD13 and CD44 were upregulated in the Apatinib group when compared to the control group, whereas the expressions of ABCG2, CD24, and ICAM-1 were downregulated." (PMID 32849930, 2020). "Lung cancer stem cell markers include the transcription factor SOX2, the metabolic marker aldehyde dehydrogenase isoform 1 (ALDH1), and the cell surface markers CD133, CD44, CD166, and ABCG2." (PMID 29698587, 2018). "In this study, we found ABCG2 and YAP1 were both overexpressed in lung cancer SP cells." (PMID 27911857, 2017). "We found co-localization of ABCG2 and the Hippo pathway effector YAP1 in lung carcinoma SP cells." (PMID 27911857, 2017). "Moreover, in lung cancer cells, gal-3 silencing increased drug sensitivity to cisplatin and paclitaxel by regulating the ABCB1 and ABCG2 transporter pumps through β-catenin." (PMID 27835877, 2016). "More specifically, TIMP-2 was determined to decrease the SP in A549 lung cancer cells through decreased transcription of ABCB1 (ATP-binding cassette sub-family G member 1), ABCG2 (ATP-binding cassette sub-family G member 2), and AKR1C1 (Aldo-keto reductase family 1 member C1)." (PMID 26056585, 2014). "In addition, BCRP/ABCG2 expression correlates with poor response to gefitinib in both cancer cell lines and lung cancer patients with wtEGFR." (PMID 21731744, 2011). "In contrast, neither gefitinib-sensitive nor gefitinib-resistant lung cancer cells carrying EGFR mutants showed BCRP/ABCG2 expression." (PMID 21731744, 2011). "In summary, this study has provided evidence that amongst reported CSC markers such as CD133, ALDH, CXCR4, ABCG2, ESA and side population staining, CD44 could be a potentially useful marker for lung cancers." (PMID 21124918, 2010). "In fact, they specifically show that ABCG2, but not mutant ABCG2, protects the lung cancer cell line A431 from Iressa-induced growth inhibition." (PMID 17875215, 2007). "The reversal effect of Tinodasertib in lung cancer cells without ABCG2 expression." (PMID 40584625, 2025). "Overall, the ABCG2 gene expression level did not correlate significantly with the age at the time of diagnosis, pathological cancer stage, cigarette smoking, ethnicity, or gender of lung cancer patients." (PMID 39457707, 2024). "We also genetically manipulated the level of LEPRE1 expression in leukemia and lung cancer cells and revealed that LEPRE1 overexpression led to increased pelitinib sensitivity via AKT activation and overexpression of ATP-binding cassette superfamily G member 2 (ABCG2)." (PMID 35190588, 2022). "Thus, paclitaxel-resistant lung cancers are more sensitive to gefitinib and readily undergo apoptotic cell death compared with non-resistant lung cancer, through downregulation of ABCB1, ABCC9, ABCG2, PLK1, and EGFR." (PMID 34503223, 2021).